STAT3 (signal transducer and activator of transcription 3)
Diseases named in the same sentence as STAT3 in open-access papers (continued):
Sharing a sentence is not in itself a finding about the gene and the disease.
osteoarthritis (56 papers, 2013 to 2026). A noninflammatory degenerative joint disease occurring chiefly in older persons, characterized by degeneration of the articular cartilage, hypertrophy of bone at the margins and changes in the synovial membrane. "Our results showed that these proteins were associated with some signaling pathways including “Osteoarthritis Pathway”, “Inhibition of Matrix Metalloproteases”, “STAT3 pathway”, “HIF1α signaling”, “NRF2-mediated Oxidative Stress Response”, and others." (PMID 38890638, 2024). "Recently, a study described that STAT3 expression is associated with the progression of several bone-related diseases, including osteoporosis, osteoarthritis and bone progression and repair." (PMID 37013568, 2023). "This is important given the positive association of increased STAT3 signaling and multiple degenerative joint diseases, including disc degeneration, disc herniation, and osteoarthritis in humans." (PMID 31652254, 2019). "This study aimed to examine the impact of STAT3 rs1053005 variation and miR-452-3p expression on osteoarthritis (OA) susceptibility and severity and the efficacy of intra-articular high-molecular-weight hyaluronic acid (HMW-HA) injection as a therapy option for knee OA." (PMID 38066785, 2023). "We recently reported that p21 deficiency induces susceptibility to osteoarthritis (OA) through signal transducer and activator of transcription 3 (STAT3)- and IL-1β-induced activation of nuclear factor kappa-light-chain-enhancer of activated B cells (NF-κB) signaling." (PMID 34131243, 2021). "The JAK2/STAT3 signaling pathway is a key regulator of various cellular functions, including survival, proliferation, and differentiation, and its persistent activation has been implicated in the progression of several diseases, such as interstitial lung diseases and osteoarthritis." (PMID 40361044, 2025). "Genetic and pharmacological translational evidence validates the p-STAT3/DCLK1 axis as a prospective therapeutic target against osteoarthritis." (PMID 42298903, 2026). "Previous research has shown that the activation of STAT3 in chondrocytes significantly contributes to cartilage degradation and osteophyte formation in osteoarthritis (OA)." (PMID 40677394, 2025). "Taken together, our findings suggest that palovarotene stimulates the Stat3 signaling pathway and that the Stat3 pathway may underlie the antitumor action of palovarotene on osteochondromas, as this pathway is involved in cartilage degeneration in osteoarthritis." (PMID 39062860, 2024). "Many independent studies have demonstrated the involvement of Stat3 signaling activation in degenerative changes in articular cartilage in osteoarthritis." (PMID 39062860, 2024). "The continuous activation of the JAK2/STAT3 pathway fosters the advancement of a variety of diseases, encompassing myeloproliferative disorders, solid tumors, interstitial lung conditions, and osteoarthritis." (PMID 38794201, 2024). "Actions of the Stat3 pathway in the context of osteoarthritis pathology include the stimulation of matrix degradation and cell death." (PMID 39062860, 2024). "Of note, STAT3, RELA, and NFKB1 transcription factors identified are considered players in key pathogenic signaling pathways in osteoarthritis." (PMID 38938688, 2024). "Previous research has shown that osteoarthritis models have much greater levels of STAT3 activation in articular cartilage." (PMID 37893118, 2023). "LncRNA GACAT3 governed IL-6/STAT3 pathway and induced proliferation of synoviocytes in osteoarthritis." (PMID 37779916, 2023). "In this review, 32 core articles were collected from PubMed, Web of Science, Embase and other platforms with "JAK2 OR STAT3" and “osteoarthritis” as keywords in recent years.." (PMID 37013568, 2023). "The terms “JAK2”, “STAT3”, and “Osteoarthritis”were used in a comprehensive literature search in PubMed to further investigate the relationship between the JAK2/STAT3 signaling pathway and OA." (PMID 37013568, 2023).
osteoarthritis (continued). "In particular, we show that CD3/ICOS costimulation plays a major role in pathways related to STAT3 function and osteoarthritis (OA), whereas the CD3/CD28 axis mainly regulates p38 MAPK signaling." (PMID 36131938, 2022). "In vitro and in vivo studies have shown that the JAK2/STAT3 pathway plays vital roles in osteoarthritis (OA)." (PMID 35563622, 2022). "Considering the key role of STAT3 in OC formation and osteoarthritis progression, STAT3 signaling was selected for further investigation." (PMID 35034537, 2022). "Expression of Stat3, a gene known to be upregulated in disc degeneration and osteoarthritis, was increased." (PMID 33735533, 2021). "A STAT3 inhibitor used to treat osteoarthritis protected against the defect, suggesting that ADGRG6 is a potential therapeutic target for IVD degeneration." (PMID 33735533, 2021). "Inhibiting STAT3 is an effective strategy to treat chronic inflammation diseases including osteoarthritis, muscle wasting, etc." (PMID 35059401, 2021). "The apoptosis of chondrocytes activated via the JAK2/signal transducer and activator of transcription 3 (STAT3) signaling pathway in osteoarthritis in vitro and in vivo model." (PMID 31212619, 2019). "Notch was found to mediated cartilage degradation, fibrosis, and osteoarthritis progression by activating the interleukin-6 (IL-6)-signal transducer and activator of transcription 3 (STAT3) and mitogen-activated protein kinase signaling pathways." (PMID 31640732, 2019). "STAT3 signaling is considered one of the major catabolic signaling pathways in osteoarthritis." (PMID 38727293, 2024). "Moreover, lncRNA DANCR influenced chondrocyte proliferation and apoptosis through regulation of miR-216a-5p, JAK2 and STAT3 pathways in osteoarthritis." (PMID 37779916, 2023). "Additionally, STAT3 signaling offers a protective function in mice against interleukin (IL)-6 induced osteoarthritis." (PMID 35034537, 2022). "The JAK2/STAT3 pathway plays an important role in osteoarthritis (OA) pathogenesis." (PMID 35563622, 2022). "Previous studies demonstrated that inhibiting the activation of the JAK2/STAT3 pathway could alleviate the degradation of osteoarthritis chondrocytes." (PMID 35747513, 2022). "Carboxymethyl chitosan could attenuate inducible nitric oxide synthase and protect against osteoarthritis through the IL-10/JAK1/STAT3 pathway." (PMID 31182999, 2019). "Previous studies showed that JAK2/STAT3 signaling pathway play important roles in osteoarthritis." (PMID 30361290, 2018). "Recently, lots study showed that JAK2/STAT3 pathway play important roles in osteoarthritis." (PMID 30361290, 2018). "In addition to the three miRNAs identified in our study, recent research has expanded our understanding of miRNAs in osteoarthritis (OA), highlighting their significant involvement in key OA-associated signaling pathways, including MMP13, STAT3, SMAD2/3, NOTCH3/Notch, and NF-κB." (PMID 39796139, 2024). "A novel p-STAT3/DCLK1/IKKβ/NF-κB axis regulates chondrocyte extracellular matrix (ECM) metabolism and drives osteoarthritis progression." (PMID 42298903, 2026). "We recognized 22 of these genes as druggable according to the DGIdb database, such as MTF1, KLC3, STAT3, LIFR, and CBFB, making them potential targets for osteoarthritis therapy." (PMID 39796139, 2024). "Kaempferol reduced the functions of lncRNA XIST and miR-130a/STAT3 on ECM degradation and inflammation in osteoarthritis." (PMID 37779916, 2023). "Previous studies suggested that RORA plays a contributory role in the pathogenesis of osteoarthritis by regulating cholesterol metabolism and IL6/STAT3 pathway." (PMID 36380336, 2022). "On comparison of the adult sheep MCA to the newborn lamb MCA, we observed only three pathways which were altered exclusively in the adult MCA, these were osteoarthritis signaling pathway, TNFR1 signaling pathway, and STAT3 pathway." (PMID 29379105, 2018).
osteoarthritis (continued). "Moreover, recent studies have further revealed the extensive roles of miRNAs in osteoarthritis, particularly in crucial pathways such as MMP13, STAT3, SMAD2/3, NOTCH3/Notch, and NF-κB signaling." (PMID 39796139, 2024). "Moreover, several transcription factors upstream of the stretch gene signature, identified by in silico analysis here (STAT3, RELA, and NFKB1), mediate osteoarthritis signaling pathways." (PMID 38938688, 2024). "Because its tyrosine phosphorylation was detected exclusively in synovial tissues of RA but not those of osteoarthritis, STAT3 is considered a crucial molecule in the pathogenesis of RA." (PMID 23406906, 2013). "Here we show that systemic inhibition of STAT3 signaling with Stattic acts to alleviate the onset and progression of endplate-oriented herniations of the IVD, which was recently also demonstrated to improve joint remodeling in a post-traumatic osteoarthritis model in mouse." (PMID 31652254, 2019).
Hepatic steatosis (55 papers, 2011 to 2026). Steatosis is a term used to denote lipid accumulation within hepatocytes. "In ob/ob and high‐fat diet‐induced obese mice, IL‐6 ameliorated fatty liver by inducing STAT3 phosphorylation, while in IL‐10 knockout mice, deficiency of IL‐6 or STAT3 led to steatosis and hepatocellular injury." (PMID 40066227, 2025). "What's more, loss of STAT5 signaling led to hepatic steatosis through elevated STAT1/STAT3 activity, which was also observed in STAT5A over‐/downexpression cells." (PMID 33155364, 2021). "IL6/STAT3-dependent molecular mechanisms driving hepatic steatosis and the pathological processes that cause NAFLD progression are still poorly understood." (PMID 30206377, 2018). "A global loss of STAT3 impairs glucose homeostasis and leads to hepatic steatosis." (PMID 39125712, 2024). "Notably, loss of STAT5 signaling results in hepatic steatosis through elevated STAT1/STAT3 activity and CD36." (PMID 33155364, 2021). "Furthermore, treatment with IL-22 activates hepatic signal transducer and activator of transcription 3 (STAT3), ameliorates hepatic oxidative stress and alcoholic fatty liver, effectively alleviate the liver damage caused by alcohol and toxicant." (PMID 32760208, 2020). "STAT3, also called acute-phase response factor, has been implicated in inflammatory signaling, inhibition of apoptosis, glucose homeostasis, hyperleptinemia, and hepatic steatosis." (PMID 24558408, 2014). "Mechanistically, HDGF promotes lipogenesis and hepatic steatosis by facilitating S6K1-dependent phosphorylation of STAT3 at Ser727." (PMID 42063330, 2026). "In fact, STAT3 exerts a positive and beneficial effect in conditions of liver damage, steatosis, fatty liver disease, or inflammation since it ensures normal liver regeneration." (PMID 41372973, 2025). "Conversely, adipocyte-specific STAT3 knockout increases body weight and leads to spontaneous hepatic steatosis." (PMID 39125712, 2024). "Curcumin inhibits the expression of SREBP1c and the suppressor of cytokine signaling 3 (SOCS-3), and it increases the phosphorylation of the hepatic activator of transcription 3 (STAT3), preventing liver steatosis." (PMID 39061866, 2024). "The incidence of fatty liver is increasing and it is necessary to further explore the functions of STAT3 in adipocyte maturation and lipolysis." (PMID 36761734, 2023). "Activation of signal transducer and activator of transcription 3 (STAT3) by interleukin-6 protects against HFD-fed-induced fatty liver and alcoholic hepatitis." (PMID 35614477, 2022). "Numerous studies have indicated that IL-22 administration activates hepatic STAT3 signaling and ameliorates several liver diseases, including autoimmune hepatitis, viral hepatitis, drug-induced liver injury, alcoholic fatty liver and steatohepatitis." (PMID 36193422, 2022). "Alcohol also directly upregulates SREBP-1c expression to cause liver steatosis by inhibiting genes regulating SREBP-1c, such as Sirtuin1 (Sirt1), adiponectin, and signal transducer and activator of transcription 3 (STAT3)." (PMID 34290612, 2021). "In our study, suppression of STAT3 activation by TSG-6 resulted in reduced hepatic steatosis and hepatic TG level, which was at odds with our assumption that STAT3 activation was localized within hepatocytes." (PMID 32116692, 2020). "mTOR, phosphorylated STAT3, phosphorylated pERK, estrogen-receptor α were found to be more frequently expressed in the hepatic steatosis group than in the control group." (PMID 29615085, 2018). "Here we investigated a possible role of a microRNAs-STAT3 pathway in the induction of hepatic steatosis." (PMID 30206377, 2018). "Overall, these results showed that phoshpo-STAT3 is induced to bind a panel of genes and miRNAs in fatty dHepaRG cells, suggesting a role in the pathogenesis of liver steatosis." (PMID 30206377, 2018).
Hepatic steatosis (continued). "Our previous study demonstrated that Gab2 recruited PI3K/Akt, suppressor of cytokine signaling 3 (Socs3)/Stat3, and other signaling molecules in fatty liver induced by pathologic factors." (PMID 28842424, 2017). "Disruption of the STAT3 gene impairs liver regeneration and activated STAT3 ameliorates fatty liver disease." (PMID 23935693, 2013). "Furthermore, elevated leptin levels have been linked to the worsening of hepatic steatosis, as leptin activates the JAK2/STAT3 pathway, increasing the expression of the suppressor of SOCS3, which contributes to hepatic lipid accumulation." (PMID 40862455, 2025). "Furthermore, limonin can reduce hepatic steatosis, lipid accumulation, and the expression of p-STAT3/STAT3, caspase-8, and prostaglandin-endoperoxide synthase 2, and improve the inflammatory response of non-alcoholic fatty liver." (PMID 39944619, 2025). "The STC2 gene was reported to ameliorate hepatic steatosis by activating STAT3 signaling in mice." (PMID 38338026, 2024). "Interestingly, the PPARG agonist Lobe mitigates hepatic steatosis and preadipocyte differentiation induced by STAT3 inactivation, highlighting the role of STAT3 in regulating lipid metabolism via PPARG." (PMID 39125712, 2024). "Furthermore, ANGPTL4 improved glucose tolerance and IR by downregulating insulin signaling pathway-associated genes, such as Akt, Janus kinase 2/signal transducer and activator of transcription-3 (JAK2/STAT3), but promoted diet-induced hepatic steatosis." (PMID 37180779, 2023). "The STAT3 pathway plays a dual role in IRI as it can also regulate lipid metabolism which may have potential for treating IRI fatty liver." (PMID 36761734, 2023). "The findings in our study indicated that MSCs- or TSG6-induced suppression of hepatic STAT3 activation might play a beneficial role in relieving liver injury, liver inflammation, and hepatic steatosis and in modulating the inflammatory responses." (PMID 31931878, 2020). "In summary, our study clearly demonstrated that TSG-6 was able to improve liver injury, alleviate oxidative stress, attenuate hepatic steatosis, induce polarization of hepatic macrophages towards a M2 phenotype and remission of hepatic inflammation, and suppress hepatic STAT3 activation." (PMID 32116692, 2020). "Therefore, we assumed that OF can bind to ASGPR to activate STAT3 in normal hepatocytes for cyto-protecting effect, since the activation of STAT3 prevents acute liver injury, fatty liver disease, and alcoholic hepatitis." (PMID 32545625, 2020). "A recent study identified p-STAT3 as a potential marker of histologic severity in hepatic steatosis, which may play a role in mechanisms of disease progression in patients with liver steatosis." (PMID 31949882, 2019). "Previous animal and cell culture studies implicated mammalian target of rapamycin (mTOR), signal transducer and activator of transcription-3 (STAT3), extracellular signal-regulated kinase (ERK) and estrogen-receptor α in the pathogenesis of hepatic steatosis and disease progression." (PMID 29615085, 2018). "Activation of a new miRNAs-phospho-STAT3 pathway that is involved in the development of hepatic steatosis may represent a target for novel therapeutic strategies and might also have potential as a biomarker for diagnosis." (PMID 30206377, 2018). "To evaluate STAT3 and miR21 implication in liver steatosis also in vivo, we treated 5 weeks aged C57/BL6 mice for 72 weeks with metformin, an established anti-diabetic drug, that is able to modulate STAT3 signaling by repressing IL-6-dependent phosphorylation of STAT320,21." (PMID 30206377, 2018). "Therefore, STAT3 has an important effect on IRI in fatty liver." (PMID 36761734, 2023). "Consistently, pharmacological inhibition of STAT3 by S3I-201 abolishes HDGF-induced lipogenic gene expression and hepatic steatosis in mouse models." (PMID 42063330, 2026). "STAT3 can inhibit hepatic fat accumulation by suppressing SREBP-1, and ultimately reduce hepatic steatosis." (PMID 36761734, 2023).
Hepatic steatosis (continued). "We examined the expression patterns of mTOR, STAT3, ERK and estrogen-receptor α in liver tissues from patients diagnosed with hepatic steatosis." (PMID 29615085, 2018). "In conclusion, here we described for the first time an integrated signaling module that links liver steatosis and the activation of IL6/STAT3 signaling with downstream STAT3-dependent activation of a number of miRNAs, including the onco-mir miR-21." (PMID 30206377, 2018). "We have also observed in vivo that reducing both phospho-STAT3 and miR-21 levels in C57BL6 mice liver, by long-term treatment with metformin, a widely used anti-diabetic drug, strongly improved age dependent hepatic steatosis." (PMID 30206377, 2018). "In addition, basic research proposed that chemerin also ameliorated liver steatosis, lobular and portal inflammation in NASH mice by promoting autophagy and alleviating oxidative stress through JAK2/STAT3 phosphorylation." (PMID 37180779, 2023). "Moreover, they found that LIF attenuated liver steatosis via binding to LIFR and activating the STAT3 pathway, which provided a rationale for LIF–LIFR to be a potential therapeutic target for NAFLD treatment." (PMID 36077090, 2022). "Caffeine was another important bioactive compound in coffee and could suppress hepatic steatosis by activating SIRT3-AMPK-ACC and signal transducer and activator of transcription 3 (STAT3) pathways." (PMID 33728021, 2021). "Loss of TKT in the liver increased apoptosis, reduced cell proliferation, decreased TNF-α, IL-6, and STAT3 levels, and alleviated DEN/HFD-induced hepatic steatosis and fibrosis, highlighting a key role for TKT in promoting genome instability during liver injury and tumor initiation." (PMID 32913470, 2020). "Treatment of fructose-induced hepatic steatosis mice with 150 mg kg−1 body weight of kefir peptides significantly inhibited the expression of the leptin receptor (OB-R) and increased the expression of p-JAK2, STAT3 and p-STAT3." (PMID 27941940, 2016). "As the inflammation in the hepatocytes is a critical transformation from simple liver steatosis to steatohepatitis, FAT10 and related TNFα/IFNγ changes via NFκB and/or STAT3 pathways could be the candidate molecular parameters for low-dose alcohol effects on alcoholic hepatitis." (PMID 32630199, 2020). "Together, these data confirm that both lowered insulin and leptin sensitivity occurred during the development of hepatic steatosis upon HFHS dieting, and suggest that the impairment in hepatic PI3K/Akt pathway may occur earlier than that in hepatic STAT3/SOCS3 pathway." (PMID 25658428, 2015). "Moreover, in fatty liver disease, ROS-induced oxidative stress can inhibit the expression of energy metabolism signaling pathway-related proteins such as AMPK, Sirtuin 1 (SIRT1), and the transcription factor signal transducer and activator of transcription 3 (STAT3)." (PMID 31159489, 2019). "The absence of IL-6 or STAT3 signaling in chronic liver inflammation enhanced HCC development, leading to an increase in hepatic steatosis, macrophage accumulation, and hepatocyte proliferation." (PMID 37627184, 2023).